BIRC5 (baculoviral IAP repeat containing 5)
Diseases named in the same sentence as BIRC5 in open-access papers (continued):
Sharing a sentence is not in itself a finding about the gene and the disease.
breast carcinoma (continued). "Copy number gain in the genes MED1 (p < 0.001), BIRC5 (p < 0.001), PRDM14 (p = 0.003), and MTDH (p = 0.003) were significantly correlated with high grade male breast cancer." (PMID 22527098, 2012). "AURKA, BIRC5, CCNB1, MKI67 and MYBL2 are well characterized genes involved in breast cancer proliferation." (PMID 22046260, 2011). "The subsequent step involved evaluating whether BIRC5, FGF1, RASSF6, SERPINE1 and STK4 could serve as targets for miRNAs differentiating breast cancer from the control." (PMID 41153630, 2025). "The qPCR and the western blot analysis results revealed that NUPR1 positively regulates the expression of the epigenetic regulator HDAC5, the anti-apoptotic molecule BIRC5, and the mitogenic receptor ERBB2 in MCF7-TamC3 and the ERBB2-enriched subtype like SK-BR-3 breast cancer cells." (PMID 39991577, 2025). "While the roles of BIRC5 and E2F1 in drug resistance in HER2 breast cancer are understood, the involvement of USP1 and TRFC remains unclear." (PMID 38534787, 2024). "Black and younger women with breast cancer have a higher burden of BIRC5-high tumors than older and non-Black women." (PMID 38515208, 2024). "Studies show that BIRC5 does not respond to neoadjuvant treatment in stage II/III breast cancer despite increased expression in stage II/II BC." (PMID 36358602, 2022). "Studies from 420 patients with long-term clinical follow-up showed that BIRC5 was found in 378 (90%) of the 420 primary breast cancer cases, and levels were substantially related to negative hormone receptor status (p = 0.0028)." (PMID 36358602, 2022). "This is not surprising, as Birc5 has recently been shown to prevent excessive autophagy as a pro-survival mechanism in breast cancer." (PMID 35836253, 2022). "So far, published studies have focused primarily on the role of the BIRC5 gene in breast cancer, and the clinical significance of other BIRC genes has not been thoroughly investigated." (PMID 33673050, 2021). "The role of the BIRC5 gene has also been identified as a prognostic factor for breast cancer patients without a pathological complete response (pCR) after neoadjuvant chemotherapy." (PMID 33673050, 2021). "The breast cancer subnetwork is found to contain (i) valid biomarkers including PIK3CA, PTEN, BRCA1, AR and EGFR; (ii) validated drug targets TOP2A, CDK4, HDAC1, IL6, BRCA1, HSP90AA1 and AR; (iii) synergistic drug targets EGFR and BIRC5." (PMID 35053185, 2021). "BIRC5 was also positively correlated with proliferation score, as this is one of the 11 proliferation markers that is included in the PAM50 gene list, which is used clinically for breast cancer subtyping and predicting patient prognosis." (PMID 32001757, 2020). "We have previously demonstrated using Microarray analysis that CD44 promotes breast cancer cell invasions and metastasis to the liver 37, and identified CTTN 15 and BIRC5 37 as downstream target genes underpinning CD44-promoted cell survival, migration and invasion." (PMID 31929744, 2020). "Although 1222 target genes of miR-10b-5p were predicted and 48 significantly negatively correlated genes were obtained, only 5 overlapped genes, BIRC5, E2F2, KIF2C, FOXM1, and MCM5, were considered as potential key targets of miR-10b-5p in breast cancer for further analysis." (PMID 31579605, 2019). "Among the listed genes, BIRC5, SEC14L2, Thymidine kinase (TK1), ZNF385B, CLIC6, ELOVL1, CHAF1B and TFF1 have been reported to have a role in early detection of cancers, tumor progression and metastasis in most of cancer types including breast cancer." (PMID 31703592, 2019). "Similarly, presence of BIRC5 protein in primary culture of canine mammary tumour cells, as well as, REM-134 canine mammary cancer cell line was determined by immuno-cytochemistry." (PMID 31530877, 2019). "Among them, NEK2, BIRC5, and TOP2A were also found to be amplified in breast cancer, suggesting that they could act as strategic players in the obese-deregulated transcriptome." (PMID 29330624, 2018).
breast carcinoma (continued). "Notably, NEK2 as well as BIRC5 and TOP2A were amplified in more than 12, 6, and 5% of breast cancers, respectively, reinforcing their potential role as key therapeutic targets." (PMID 29330624, 2018). "However, BIRC5 has not been well studied among racially diverse populations where aggressive breast cancers are prevalent." (PMID 38515208, 2024). "TCGA BIRC5 RNA sequencing data from 33 different cancer types and matching normal tissue samples for 16 cancer types were downloaded from Broad GDAC Firehose and validated using breast cancer microarray data from our previous work and data sets from the GENT2 web-based tool." (PMID 35331169, 2022). "Moreover, it was demonstrated that BIRC5 was a pejorative marker in stage II/III breast cancer with no response to neoadjuvant chemotherapy." (PMID 32043523, 2020). "Notably, BIRC5 and FOXM1 expression was also reduced in taxane-treated breast cancer patients, and FOXM1 expression was upregulated in most of the PTXR TNBC cell lines consistent with its established role in drug resistance to genotoxic agents, such as taxane and epirubicin." (PMID 28187446, 2017). "Likewise, a statistically significant downregulation of BIRC5 transcription as well as FOXM1 expression was obtained in breast cancer patients irrespective of their subclass, as well as in TNBC patients." (PMID 28187446, 2017). "Furthermore, BIRC5 was expressed over two-fold higher in estrogen receptor-negative (ER−) breast cancers compared to estrogen receptor-positive (ER+) breast cancers (p = 9e-46)." (PMID 25763854, 2015). "To investigate whether the 3’-UTRs of BIRC5 and LASP1 are functional targets of miR-203 in breast cancer cells, we co-transfected the miR-203 precursor (or control miRNA) and pMIR-BIRC5-3’-UTR plasmid (or mutant) or pMIR-LASP1-3’-UTR plasmid (or mutant) into cells." (PMID 22713668, 2012). "Expression profiling indicated upregulation of BIRC5 and SERPINE1 independent of breast cancer subtype." (PMID 41153630, 2025). "BIRC5, FGF1 and RASSF6 are unlikely to be targets of miRNAs significantly altered across five breast cancer subtypes in this study." (PMID 41153630, 2025). "The present study also showed that gain of DEK and BIRC5 genes, which seems not to be involved in the PI3K or ER pathway, had clear prognostic significance in patients with breast cancer, suggesting presence of other pathways exhibiting crosstalk with the PI3K or ER pathway." (PMID 23679233, 2013).
lung cancer (51 papers, 2011 to 2026). A malignant neoplasm involving the lung. "BIRC5 was identified as a risk factor that promotes lung cancer progression, particularly in patients with Pathologic T2 stage, N0 stage, M0 stage, and residual tumor status (R0), as well as in patients of all age groups." (PMID 39703228, 2024). "To explore BIRC5’s specific role in LUAD, we identified the top 50 genes associated with BIRC5 in lung cancer datasets." (PMID 39703228, 2024). "Further analysis of genes co-expressed with BIRC5 in lung cancer revealed eight genes significantly associated with prognosis, as determined by univariate Cox regression analysis." (PMID 39703228, 2024). "BIRC5 was associated with a bad prognosis in lung cancers by favoring mitotic cell cycle-related pathways." (PMID 35884522, 2022). "High expression of BIRC5 is associated with poor prognosis in patients with hepatocellular and pancreatic cancer, lung cancer, renal papillary cell carcinoma, renal clear cell carcinoma, endometrial carcinoma, and sarcoma." (PMID 33431968, 2021). "To determine the role of BIRC5 in lung cancer, we first evaluated its expression and diagnostic and prognostic value in patients with NSCLC." (PMID 34804966, 2021). "There has been also many studies showing that urine BIRC5 level can be used as a diagnostic indicator of bladder cancer and lung cancer." (PMID 34712656, 2021). "Silencing of BIRC5 also caused proliferation inhibition and induced apoptosis in lung cancer cells." (PMID 34804966, 2021). "However, up to date, the BIRC5 -31C/G polymorphism was only reported to be associated with risks of lung cancer, urothelial carcinoma, sporadic colorectal cancer, gastric cancer and NPC in the present study." (PMID 21304814, 2011). "The stacked bar graph showed a positive correlation between BIRC5 expression and immune cell infiltration in lung cancer." (PMID 39703228, 2024). "Next, we investigated the role of BIRC5 in patient prognosis and disease progression across various clinical features of lung cancer." (PMID 39703228, 2024). "We first explored the genomic alterations of BIRC5 in lung cancer using the cBioPortal website and found that BIRC5 genomic changes occurred in 2.4% of cases." (PMID 39703228, 2024). "Focusing on lung cancer as a representative tumor type, we further analyzed the correlation between BIRC5 and immune cell infiltration." (PMID 39703228, 2024). "Expanding this analysis to include LUSC would provide a more comprehensive view of BIRC5’s role across lung cancer subtypes, serving as a logical continuation of this research." (PMID 39703228, 2024). "Consistent with the CCK-8 and colony formation experiments, the EdU assay further confirmed that silencing BIRC5 remarkably suppressed lung cancer cell proliferation, highlighting its oncogenic role." (PMID 37741993, 2023). "This will enable us to gain a more comprehensive understanding of the role of BIRC5 in lung adenocarcinoma and identify new personalized treatment targets for the clinical diagnosis and management of lung cancer." (PMID 37834111, 2023). "Five of the seven genes (BIRC5, GIMAP5, HBB, IL33, and AKAP12) associated with the LC-LK alignments have been observed to be deregulated in lung cancer." (PMID 36101460, 2022). "More importantly, BIRC5 promotes lung cancer progression partially by modulating PD-L1 expression via mTOR signaling and inducing tumor immune evasion." (PMID 36046648, 2022). "From GEO data, we selected DEGs of the number of afatinib-resistant cells, lung cancer and normal tissues, and selected BIRC5 for further research." (PMID 34804966, 2021). "In order to further confirm the clinical value of BIRC5 expression in the diagnosis of lung cancer, we further analyzed TCGA dataset, and the results were shown to be consistent with the observations in the Oncomine data." (PMID 34804966, 2021). "In the current study, we first focused on the expression features value of BIRC5 in afatinib-resistant lung cancer." (PMID 34804966, 2021).
lung cancer (continued). "BIRC5 is highly expressed in lung cancer and enhances the prognostic value of platinum-based therapies by decreasing BIRC5 expression." (PMID 33431968, 2021). "Compared to other IAPs, survivin, encoded by the BIRC5 gene, is the smallest and most extensive studied member of the IAP family in lung cancer." (PMID 34439255, 2021). "OA treatment was able to effectively reduce BIRC5 expression in lung cancer, ovarian cell carcinoma, and leukaemia as well as XIAP expression in hepatocellular carcinoma." (PMID 28791312, 2017). "BIRC5 gene amplification was also observed in lung cancer using multiplex ligation-dependent probe amplification (MLPA) technique." (PMID 27372966, 2016). "In lung cancer, research into BIRC5 has mainly concentrated on NSCLC." (PMID 38556560, 2024). "Moreover, in vitro functional experiments demonstrated that BIRC5 enhances the proliferative, migratory, and invasive capacities of lung cancer cells, supporting its potential as a therapeutic target." (PMID 39703228, 2024). "BIRC5 expression levels were augmented in tissues of lung cancer patients." (PMID 34372869, 2021). "We have demonstrated that overexpression of BIRC5 resulted in resistance to afatinib in NSCLC, and BIRC5-specific inhibitors may reverse the resistant phenotype and promote cell death of lung cancer cells." (PMID 34804966, 2021). "Previous research revealed that BIRC5 was elevated and promoted the development of lung cancer." (PMID 34820377, 2021). "Moreover, BIRC5 was found to be a biomarker for prognosis and therapy in other types of cancers, including lung cancer and pancreatic cancer." (PMID 32662515, 2020). "Additionally, the Human Protein Atlas resource revealed high expression of BIRC5 or PLK1 to be associated with poor survival in renal, liver, and lung cancer patients and high expression of ROCK1 to be a marker of unfavorable prognosis in pancreatic cancer." (PMID 31523390, 2019). "However, our study found that BIRC5’s prognostic significance may vary across cancer stages, with its impact being more pronounced in early-stage cancers, such as early-stage lung cancer, but less significant in later TNM stages." (PMID 39703228, 2024). "In addition, we investigated how BIRC5 affected PD-L1 expression in lung cancer cells in vivo." (PMID 36046648, 2022). "However, little research has explored BIRC5 in the context of afatinib resistance in lung cancer." (PMID 34804966, 2021). "XIAP (BIRC4), Survivin (BIRC5), Livin (BIRC7), and BRUCE or Apollone ((BIRC6) are four members of the IAP family that play an important role in the development of chemoresistant lung cancer." (PMID 36800962, 2023). "However, in lung cancer, high expression of BIRC5 may prolong OS and DFS." (PMID 34917126, 2021). "In this study, we obtained eight lung cancer-related genes (CDC25C, TWIST1, HIF1A, DNMT1, PARP1, CDKN1A, CCNB1, and BIRC5) as seed nodes, using an RWR algorithm analysis to prioritize lung cancer related genes." (PMID 33193600, 2020). "BIRC5, commonly known as SURVIVIN, is a gene recognized for its strong pan-cancer prognostic value and pro-oncogenic activity in a wide variety of malignancies, particularly in lung cancer." (PMID 41596324, 2026). "BIRC5 has been shown to regulate key pathways involved in EMT, including Wnt/β-catenin and TGF-β signaling, which contribute to metastatic progression in ovarian and lung cancers." (PMID 41244050, 2025). "Results showed that the mRNA expression of BIRC5, SHCBP1, CCNA2, SKA3 and GINS1 in LUAD and LUSC tissues were all significantly higher than that in normal tissues, whereas only BIRC5 and CCNA2 protein expression in lung cancer tissues were much higher than those in the normal lung tissues." (PMID 34806315, 2022).
lung cancer (continued). "Finally, by establishing an afatinib-resistant lung cancer cell line in vitro, HCC827-AR, we further confirmed that BIRC5 was overexpressed in lung adenocarcinoma cell line afatinib resistant cells at the protein levels." (PMID 34804966, 2021). "Nevertheless, we suggested that BIRC5, FGF2, RTKN2 and SLIT3 may be important for lung cancer; but experiment verification should be performed in future." (PMID 32299382, 2020). "IRF1 is downregulated in lung cancer, IPF and PAH datasets, probably because it represses the expression of genes involved in anti-proliferative response, such as BIRC5/survivin, CCNB1, CCNE1, CDK1, CDK2 and CDK4 and in immune response, such as FOXP3, IL4, ANXA2 and TLR4." (PMID 31867044, 2019). "A recent study demonstrated that circulating levels of IgG antibodies against linear peptide antigens derived from baculoviral IAP repeat‐containing protein 5 isoform 2 (BIRC5) and myc proto‐oncogene protein (MYC) were significantly increased in nonsmall cell lung cancer (NSCLC)." (PMID 29744296, 2018). "Furthermore, Survivin/BIRC5 interacted closely with molecules which were shown to regulate stem cell properties in lung adenocarcinomas (SPC25), influence radiosensitivity in lung cancer (AURKA), or mediate anti-EGFR therapy in NSCLC (AURKB)." (PMID 32039023, 2019).
ovarian carcinoma (48 papers, 2011 to 2025). A malignant neoplasm originating from the surface ovarian epithelium. "On the other hand, BIRC5 overexpression is related to adverse outcome in breast, lung, colorectal, prostate, and ovarian cancer and is thought to be a promising cancer diagnostic biomarker." (PMID 34712656, 2021). "In conclusion, our study demonstrated that BIRC5 is highly expressed in ovarian cancer cells and associated with a patient’s poor survival or prognosis." (PMID 29212257, 2017). "However, as many as five BIRC5 polymorphisms were associated with the age of onset, a phenomenon which was previously observed only in ovarian cancer patients." (PMID 31467536, 2019). "Several BIRC5 polymorphisms were shown to be associated with susceptibility (gastric, bladder, and hepatocellular), survival (colorectal and breast), or age of onset (ovarian cancer)." (PMID 31467536, 2019). "Several BIRC5 polymorphisms have been studied and have been associated with susceptibility to lung, gastric, bladder, oral, and liver cancer as well as age of onset in ovarian cancer and survival in colorectal cancer and breast cancer." (PMID 30736319, 2019). "The loss of BIRC5 expression inhibited EMT in ovarian cancer cells and suggested that BIRC5 may affect cell motility and invasion." (PMID 29212257, 2017). "Moreover, upregulated BIRC5 was associated with poor prognosis of ovarian cancer." (PMID 35178302, 2022). "Consistent with this, targeting of BIRC5 in ovarian cancer has previously been found to reduce migration and invasion in vitro, and metastasis in vivo." (PMID 38711848, 2024). "FOXM1 knockdown also reduced the mRNA levels of survivin/BIRC5, suggesting that the BIRC5 gene was a transcriptional target of FOXM1 in ovarian cancer cells just as in other cell types reported previously." (PMID 37445993, 2023). "A vaccine designed against BIRC5 HLA class I peptide generated strong antigen-specific immune responses in ovarian cancer patients." (PMID 33431968, 2021). "In SKOV3 and OVAR3 ovarian cancer cell lines, high expression of miR-203 leads to restrain of EMT process by linking to BIRC5 and causes its downregulation and attenuates the TGF-β signal transduction pathway." (PMID 33413466, 2021). "BIRC5 is reportedly upregulated in ovarian cancer cells, and its inhibition impeded the growth and migration of ovarian cancer cells." (PMID 32265985, 2020). "It is worth noticing that miR‐203 inhibits the EMT of ovarian cancer cell line by targeting survivin/BIRC5 and blocking TGF‐β signal pathway." (PMID 33058500, 2020). "MiR‐203 inhibits the EMT of ovarian cancer cell line by targeting BIRC5 and blocking TGF‐β signal pathway." (PMID 33058500, 2020). "In paclitaxel-resistant ovarian cancer cells, blocking of STAT3 activity suppresses STAT3 downstream antiapoptotic regulatory genes BCL2L1, MCL1, and BIRC5, which increases paclitaxel sensitivity in paclitaxel-resistant ovarian cancer cells in vitro." (PMID 31861720, 2019). "Here we demonstrated that miR-203-targeted BIRC5, whose expression is significantly upregulated in ovarian cancer compared to normal controls." (PMID 30241553, 2018). "We showed previously that TGFβ promotes BIRC5 expression in ovarian cancer cells, and that knockout of BIRC5 or inhibition of BIRC5 with YM155 attenuated the TGFβ pathway." (PMID 30241553, 2018). "miR-203 expression also inhibits ovarian tumor metastasis by targeting BIRC5 and attenuating the TGFβ pathway in an orthotopic ovarian cancer mouse model." (PMID 30241553, 2018). "In ovarian cancer miR-203 expression is significantly reduced, while BIRC5 is highly expressed, as we published previously." (PMID 30241553, 2018). "We also analyzed 185 ovarian carcinomas and 10 normal ovarian surface epithelia in the Oncomine database, and BIRC5 expression was significantly higher in tumors than in controls with approximately a 4-fold increase." (PMID 29212257, 2017).